IGF1R (insulin like growth factor 1 receptor)
Diseases named in the same sentence as IGF1R in open-access papers (continued):
Sharing a sentence is not in itself a finding about the gene and the disease.
tumor (continued). "The expression of IGF-1R is positively correlated with the expression of CD276 in most cancer types, and since CD276 is related to immunosuppression, this may explain why the increased expression of IGF-1R in tumor has an impact on the prognosis." (PMID 34804946, 2021). "Interestingly, previous studies demonstrated that IGF1R regulated cancer cell metastasis to bone and tumor growth." (PMID 34185427, 2021). "The role of the IGF-1R pathway in promoting tumor growth and survival is well established." (PMID 33829018, 2021). "MiR-152 acts on the angiogenesis pathway as a tumor suppressor, leading to IGF-1R blockade." (PMID 33419057, 2021). "However, recent clinical trial results have proved disappointing, with IGF1R-targeted approaches activating the insulin receptor to promote tumor growth." (PMID 33723215, 2021). "Studies using a β-3 adrenergic receptor agonist to reduce circulating insulin levels or using a tyrosine kinase inhibitor that inhibited both the IR and IGF-1R reported reduced the tumor growth in MKR mice, further supporting our in vivo observation with DZ71–73." (PMID 33495474, 2021). "LL6 showed quite variable impact on IGF-1R and Src activation in xenograft tumor models, which might be due to the tumor heterogeneity." (PMID 33408789, 2021). "Indeed, transient IGF-1R inhibition combined with continuous osimertinib eradicated tumors and provided durable tumor growth inhibition even after cessation of osimertinib." (PMID 34830794, 2021). "Notably, high level of let-7e improves CRC radio- and chemosensitivity, and therefore limit tumour progression, via a direct interaction with IGF1R." (PMID 33901189, 2021). "Our study uncovers a novel molecular mechanism by which the m6A‐induced PCAT6/IGF2BP2/IGF1R axis promotes PCa bone metastasis and tumor growth, suggesting that PCAT6 may serve as a promising prognostic marker and therapeutic target against bone‐metastatic PCa." (PMID 34185427, 2021). "Knockdown of CXCR4 expression level via applying a CRISPR/Cas9 genome editing system in CRC cells could inhibit tumor angiogenesis triggered via IGF1R with the help of SDF-1 in the tumor microenvironment." (PMID 33768092, 2021). "A deeper understanding of the biological relevance of this network of IGF1R modulators might provide novel therapeutic opportunities to block this system in neoplasia." (PMID 33673232, 2021). "A series of studies have indicated that IGF1R is closely related to tumor drug resistance." (PMID 34876132, 2021). "A positive correlation was found between the MMP‐2 and IGF‐1R expression in OSCC tumours." (PMID 34528373, 2021). "We evaluated 4497 CRC samples from 1499 patients for the expression of IGF1R in tumor cells." (PMID 32727431, 2020). "In some malignancies, overexpression of IGF1R promotes tumor growth, invasion, and metastasis." (PMID 32963562, 2020). "Western blot analysis demonstrated that while the evaluated EGFR-mutated NSCLC cell lines expressed various levels of IGF-1R protein, AXL-low-expressing tumor cells reported higher levels of phosphorylated IGF-1R (pIGF-1R) compared to AXL-high tumor cell lines." (PMID 32929081, 2020). "Our data suggest further investigation of IGF-1R inhibitors in combination with MEK inhibition and dexamethasone, possibly in those patients whose tumor cells show amplification of IGF-1R or elevated expression of NDRG1, may be warranted." (PMID 32228485, 2020). "On the other hand, while AXL-low-expressing tumor cells are highly sensitive to osimertinib, a small population of these cells demonstrates tolerance due to the increased expression and phosphorylation of IGF-1R." (PMID 32929081, 2020). "IGF1R expression is frequent and biologically relevant in CRC and was associated with tumor localization, an MMR proficient CRC phenotype, more differentiated tumors, less lymphatic vessel invasion and a lower tumor size at diagnosis." (PMID 32727431, 2020).
tumor (continued). "In addition, immunochemistry results showed that over-expression of ASB16-AS1 reduced the levels of CDK6 and IGF1R in xenografted tumor tissues." (PMID 33219221, 2020). "Furthermore, the reason why baseline level expression of phosphorylated IGF-1R is higher in the AXL-low-expressing tumor cells than that in the AXL-high-expressing tumor cells is also unclear at present." (PMID 32929081, 2020). "In animal models, MEDI-573 blocks tumor growth by halting the IGF-1R and IR-A signaling cascade." (PMID 33364239, 2020). "IGF1R expression is often misregulated in tumor cells, but the relevance of this for cancer progression remains unclear." (PMID 32033461, 2020). "Coimmunoprecipitation (Co‐IP) assay confirmed that PDGFRα and IGF1R from mouse tumor OPCs could form complex (through both ectopic expression and directly testing the endogenous proteins), either through direct or indirect interaction." (PMID 33173731, 2020). "Besides, ciRS-7 can abrogate the tumor-suppressive effect of miR-7 via different cancer-associated signaling pathways including EGFR, PTEN/PI3K/AKT, NF-κB, and IGF1R." (PMID 32090067, 2020). "To directly determine whether the IGF1R is activated in human tumor OPCs, we analyzed the tumor tissue from a GBM patient with the classical subtype." (PMID 33173731, 2020). "However, clinical studies showed that inhibition of IGF-1R has very limited efficacy due to the development of resistance to IGF-1R blockade in tumor cells." (PMID 32843616, 2020). "This suggests that IGF1R may regulate OPCs mainly via the downstream PI3K‐Akt pathways throughout the tumor development stages." (PMID 33173731, 2020). "miR-99b-5p/203a-3p and miR-99b-5p/203a-3p may function as tumor suppressive miRNAs by negatively regulating IGF-1R expression in GC cells." (PMID 32218690, 2020). "However, cytoplasmic IGF1R-expression correlated significantly with the IR status in tumor cells (p < 0.001), albeit." (PMID 32727431, 2020). "The mRNA expression of IGF1R in tumor tissues was significantly higher than that in normal tissues." (PMID 32847606, 2020). "Suppression of IGF-1R in BC cells was shown to inhibit the tumor promoting effect of adipocytes." (PMID 32120856, 2020). "Disruption of the IGF-2/IGF-1R circuit abolishes CD74-NRG1-mediated tumor-initiating ability." (PMID 33511137, 2020). "We found that combinatorial therapy of PPP1R1A inhibition with an IGF-1R inhibitor was more effective not only in limiting primary xenograft tumor growth, but also in decreasing lung metastasis, demonstrating a promising specific strategy to treat both primary and metastatic ES." (PMID 32477459, 2020). "Deregulation of IGF1R signal transduction inhibits tumor development, progression, and metastasis." (PMID 32971893, 2020). "Similar to breast cancer, KL might be tumor-suppressing by inhibiting IGF-1R–dependent PI3K/AKT signaling or aerobic glycolysis via ERK/hypoxia-inducible factor 1α (HIF-1α) in CRC." (PMID 33520985, 2020). "Similarly, the tumor cell tissues with higher proliferation (such as colon epithelium) showed induction of both γH2AX and IGF1R/PCNA." (PMID 32701997, 2020). "Since we hypothesized that phosphorylation of IGF‐1R would be predictive for tamoxifen resistance, we only selected tumor samples harboring IGF‐1R expression to evaluate the p‐IGF‐1R/InsR scoring." (PMID 31490549, 2020). "Only three out of nine tumour samples expressed IGF-1R at the basal level." (PMID 31988347, 2020). "Interestingly, the IGF-1R expressions in these patients associated with high stromal abundance, suggesting the regulation of tumor-stromal crosstalk via IGF/IGF-1R signaling." (PMID 32660466, 2020). "Adequate tumor tissue for IGF-1R expression was available in 15 of the 17 cases." (PMID 32976223, 2020).
tumor (continued). "In 402 (26.8%) cases all tumor cells showed a weak (cCC-IGF1R 1+) immunostaining and in 4 (0.3%) cases 90% of all tumor cells within a given sample showed a strong cytoplasmic IGF1R expression (cCC-IGF1R 2+).The median HScore for cCC-IGF1R was 90 (range 0–190)." (PMID 32727431, 2020). "Moreover, among these nine tumours, only three tumours expressed IGF-1R at the basal level, and this expression decreased upon LA treatment." (PMID 31988347, 2020). "Thus, IGF-2R is thought to suppress tumor growth and proliferation by indirectly suppressing IGF-1R activation." (PMID 33143702, 2020). "IR and IGF-1R IHC staining was performed on 196 available tumor specimens." (PMID 32393319, 2020). "Histogram analysis demonstrated that 99.6% of tumor cells presented high IGF1R expression." (PMID 32899449, 2020). "Upregulated IGF-1R or its ligands have been observed in several tumor types." (PMID 31467485, 2019). "Unlike other tyrosine kinase growth factor receptors, tumours have not been found to harbour activating mutations in IGF1R, not even as a resistance mechanism in response to IGF1R‐targeted therapies." (PMID 31179642, 2019). "Zhao and Gu reported that the silencing of IGF-1R enhances the radiation sensitivity of human esophageal squamous cell carcinoma, leading to tumor growth delay and prolonged survival after radiotherapy in a tumor xenograft model in vivo." (PMID 30621219, 2019). "GSTZ1‐1 functions as an important tumor suppressor by inhibiting NRF2/IGF1R axis in HCC." (PMID 31267557, 2019). "Moreover, our findings are in agreement with a large literature that links IGF-1R with tumor progression." (PMID 31160622, 2019). "IGF2 and IGF1R were highly expressed by three HGNET-BCOR tumor samples and PhKh1 cells." (PMID 31234291, 2019). "Also, an over-expression of IGF-1/IGF-1R signaling also contributes to tumor cell survival, metastasis, and resistance to chemotherapy protocols." (PMID 30881341, 2019). "Not only is IGF-1R expression necessary for malignant transformation by numerous major oncogenes, but receptor inhibition (either by suppressing expression or activation) has been shown to lead to tumor cell growth inhibition." (PMID 31600876, 2019). "The expression of IGF1R was confirmed at the protein level for the P1 tumor." (PMID 31234291, 2019). "Furthermore, miRNA-375 inhibits tumor growth and metastasis through repressing IGF-1R that has been identified as a potential therapeutic target for NSCLC patients." (PMID 30621620, 2019). "As in the case of insulin and IR, the expression of the ligand (IGF1) and its receptor (IGF1R) within the same tumor could provide proof of an autocrine-paracrine signaling loop of RCC cells stimulation." (PMID 30929166, 2019). "Besides IGF-1R, other receptor tyrosine kinases (RTKs) active in ES have been explored as potential therapeutic targets given the key role of RTKs in tumor growth and survival, and the success of RTK-inhibitors in other cancers." (PMID 31275859, 2019). "Moreover, inhibition of IGF1R or NRF2 significantly inhibited tumor‐promoting effects of GSTZ1 knockout in vivo." (PMID 31267557, 2019). "Activation of IGF-1R promotes mitosis and reduces apoptosis of tumor cells." (PMID 31555212, 2019). "We infer that Bru inhibits the NRF2/IGF1R axis in Gstz1−/− mice, inducing apoptosis of tumor cells." (PMID 31267557, 2019). "Interestingly, since in vivo tumour growth suppression was incomplete, remission was achieved by combining trametinib with the IGF1R inhibitor." (PMID 31126017, 2019). "To evaluate if the targeting of the SHH and the IGF1R pathway could affect the growth of the tumor and to prioritize related drugs, we tested the effect of relevant drugs on the tumor cells (225ZL) isolated from the first relapse of the patient." (PMID 31480400, 2019). "Moreover, chemotherapies have been shown to increase expression of both IGF-1R and ErbB3 in tumor cell lines, rendering these resistant to cytotoxic therapies." (PMID 31728045, 2019).
tumor (continued). "We subsequently generated orthotopic xenografts to evaluate tumorigenicity using these same pretreated GPC lines where, as expected, dual inhibition of STAT3 and IGF-1R conferred the greatest survival benefit and extended tumor latency in the STAT3-low group of mice." (PMID 31399589, 2019). "The expression of IGF-1R in tumor tissue may differ from normal breast tissue or pathways involving IGF-1R may differ by menopausal status." (PMID 30497427, 2018). "Taken together, our data revealed that IGF-1R is a direct co-target of miR-99b-5p/203a-3p, and miR-99b-5p/203a-3p may function as tumor suppressive miRNAs by negatively regulating IGF-1R expression in GC cells." (PMID 29973668, 2018). "IGF-1 is a factor essential for cell growth, proliferation and differentiation and preclinical studies in NET cell lines have demonstrated that over-expression of IGF-1 and/or IGF-1R, can induce tumor cell proliferation and raise Chromogranin A (CgA) synthesis." (PMID 29854305, 2018). "The IGF-1R siRNA inhibit 60% of tumor growth in comparison to control group." (PMID 29861465, 2018). "Importantly, IL-6 and CCL2 production in mouse and human tumor epithelial cells is elevated with reduced IGF-1R function." (PMID 30458886, 2018). "We showed that inhibition of IGF-1R in tumor epithelium results in activation of the EnR stress pathway and upregulation of PDI suggesting that the increased ROS production may be through amplified EnR stress." (PMID 30458886, 2018). "Although monocyte recruitment is increased in tumors with attenuated IGF-1R signaling, it is still unclear whether these monocytes become tumor-degrading or tumor-promoting macrophages." (PMID 30458886, 2018). "However, while SSTR agonists have been shown to have anti-tumor growth activity, IGF-1R inhibition proved to be ineffective in treatment of NETs." (PMID 29973528, 2018). "On the contrary, there is data showing low IGF1R expression in HCC tumor samples." (PMID 29702590, 2018). "On the basis of our findings, we propose that GBM tumor growth is characterized by a structured population with less aggressive clones (TMZ-sensitive-IGFBP6+-IFG-1R−) that block the expansion of more aggressive cells (TMZ-resistant-IGF2+IGF-1R+)." (PMID 30231881, 2018). "This is highly required especially because clinical responses to anti-IGF1R is observed in approximately 15% in ES, the tumor type with the best response to this targeted approach, while clinical response was registered in only a small (1–5%) but distinct proportion of patients with solid tumors." (PMID 29731738, 2018). "Consistently, when 4T1 tumor-bearing mice with myeloid TβRII deficiency (TβRIIMyeKO) or wildtype were treated with NT157, an inhibitor of IGF1R signaling, there was a synergistic anti-metastasis effect compared with that from TβRIIMyeKO or NT157 treatment alone." (PMID 29973593, 2018). "We demonstrate that miR-130a and miR-145 targeting myeloid TGFβ signaling or IGF1R inhibitor could be exploited to decrease tumor metastasis through improved anti-tumor immunity." (PMID 29973593, 2018). "We have defined IGF-1R as a negative regulator of cytokine production by protecting epithelial cells from oxidative stress, resulting in maintenance of a tumor microenvironment that suppresses tumor cell invasion." (PMID 30458886, 2018). "Thus, in the current studies, the effect of IGF1R signaling pathway on immunosuppression of Gr-1+CD11b+ cells and metastasis phenotype were further investigated in 4T1 tumor-bearing mice treated with NT157." (PMID 29973593, 2018). "We determined that IGF-1R is essential in tumor suppression in breast tumorigenesis." (PMID 30458886, 2018). "Furthermore, treatment of cells with GDC0032 increases the expression of IGF1R in both tumor cell line models." (PMID 30237504, 2018). "In addition to TβRII, miR-130a and miR-145 also target multiple mediators in the IGF1R signaling pathway that correlated with tumor stage of cancer patients." (PMID 29973593, 2018).
tumor (continued). "Phosphorylation of INSR-B, caused by insulin binding, preferentially induces metabolic signals via the PI3K pathway, while phosphorylation of INSR-A and IGF1R by insulin, predominantly leads to cell growth, and potentially tumor growth, via activation of the MAPK-ERK pathway." (PMID 29486734, 2018). "Taken together, these results demonstrated that MMP‐1 secreted by MSCs could efficiently cleave the IGF‐2/IGFBP2 complex, facilitating the migration of MSCs toward tumor cells via the IGF‐2/IGF‐1R signaling axis." (PMID 29321953, 2018). "Thus, upon reduction of miR-376a expression, as is seen in SMZL, IGF1R becomes fully activated, promoting tumor progression." (PMID 30042829, 2018). "Our data support the hypothesis that reduction of IGF-1R function increases cellular stress and cytokine production to promote an aggressive tumor microenvironment through infiltration of immune cells and matrix remodeling." (PMID 30458886, 2018). "The expression level of IGF1R was analysed in tumour samples by RT‐qPCR." (PMID 29160922, 2018). "Similarly, the IGF-1/IGF-1R axis can stimulate other concurrent oncogenic mechanisms in tumor cells, such as androgen receptor signaling in prostate and in colon cancer cells." (PMID 30111747, 2018). "However, elevated expression of IGF-1R within tumor samples from patients with GBM correlated with poor outcome." (PMID 30231881, 2018). "IGFBP7 binds the IGF1R and functions as a candidate tumor suppressor." (PMID 29702590, 2018). "The observed impact of coffee consumption on tumor-specific IGF1R levels in relation to BMI suggests that coffee intake as well as BMI could be of importance in studies regarding IGF1R targeting treatments." (PMID 29928262, 2018). "The risk of death for patients with IGF-1R overexpression increases 70% compared to ccRCC patients with tumours without IGF-1R expression." (PMID 29527128, 2018). "The levels of co-expression of IGF-1R and multidrug resistance-associated protein-1 (MRP-1) in the tumor may predict the effect of chemotherapy." (PMID 30111747, 2018). "While the effect of IGF1R signaling on tumor cells is well established, the effect on the immune response of a tumor-bearing host is unknown." (PMID 29973593, 2018). "We further tested whether increased IL-6 and CCL2 expression in tumor epithelial cells is a direct result of increased cellular stress in response to IGF-1R inhibition." (PMID 30458886, 2018). "Importantly, miR-130a and miR-145 mimics, as well as IGF1R inhibitor NT157 significantly decreased tumor metastasis." (PMID 29973593, 2018). "Their results indicated that engaging the IGF-1/IGF-1R system might enable tumor cells to escape anti-EGFR-mediated treatment as a consequence of IGF-1-driven stimulation of the PI3K–Akt pathway." (PMID 28423026, 2017). "Our results revealed that miR-29a-3p is a tumor suppressor gene that acts by directly repressing the oncogene IGF1R, which takes part in immunoregulation in tumor microenvironments in HCC, implying that miR-29a-3p could be a potential target for HCC treatment." (PMID 29156819, 2017). "We evaluated the frequency of MRAS mutation and IGF1R amplification using macrodissected tumor DNA to remove as much as possible of the nontumor tissue." (PMID 27891760, 2017). "The expression of IGF1R is higher in HCC than in adjacent non-tumor tissue samples." (PMID 29156819, 2017). "OSI-906 (linsitinib), an anti-tumor drug, is an orally bioavailable dual inhibitor of IR and IGF1R." (PMID 28646158, 2017). "Importantly, the anti-IGF-1R treatment significantly reduced tumor cell proliferation independently of growth site, with the maximum decrease (24%) observed within the bone marrow cavity when NVP-AEW541 was given in combination with castration." (PMID 28447314, 2017). "However, the IGF-2/IR-A loop appears to be more important than the IGF-1/IGF-1R loop in thyroid cells with dedifferentiated and stem-like phenotype involved in tumor progression and metastasis." (PMID 29184536, 2017).